FHL3 (four and a half LIM domains 3)
Diseases named in the same sentence as FHL3 in open-access papers (continued):
Sharing a sentence is not in itself a finding about the gene and the disease.
tumor (continued). "Moreover, the fluorescence intensity, tumor volume, and Ki67-positive rate were greater in the FHL3 overexpressing group than in the control group, whereas FHL3 knockdown hindered tumor growth." (PMID 41184244, 2025). "In addition, the orthotopic liver tumor assay results demonstrated that FHL3 knockdown reversed the increase in total flux, tumor volume, Ki67 positivity, and lung metastasis induced by YAP." (PMID 41184244, 2025). "In addition, KRAS knockdown inhibited FHL3-mediated promotion of subcutaneous tumor growth in mice, with a low percentage of Ki67-positive tumors." (PMID 41184244, 2025). "Moreover, the results of the subcutaneous tumor model also suggested that FHL3 knockdown negated the proliferation promoting effect of YAP in mice." (PMID 41184244, 2025). "In contrast, FHL3 knockdown inhibited the increase in tumor volume and weight in the MHCC97H group." (PMID 41184244, 2025). "FHL3 was first recognized as a tumor suppressor due to its interactions with other proteins." (PMID 35686099, 2022). "FHL3-mediated tumor growth has also been reported in glioma, breast cancer and liver cancer." (PMID 31935687, 2020). "In addition, FHL3 was overexpressed in PDAC tissue compared with its expression in adjacent non-tumor tissue in 49 paired paraffin-embedded sections of PDAC samples (p<0.001), as same as the outcome of WB in eight matched fresh frozen PDAC samples (p<0.01)." (PMID 31935687, 2020). "Based on the previous and present experimental results, FHL3 may play a tumor suppressor—like role in certain cancer cells and the function of Ang appears to be mechanistically linked to the expression of FHL3 protein." (PMID 25659096, 2015). "First, we assessed the expression of FHL3 in all the tumor and normal tissues." (PMID 25659096, 2015). "Therefore, we further explored the effects of FHL3 on tumor growth and lung metastasis in vivo." (PMID 41184244, 2025). "In addition, the knockdown of FHL3 was found to reduce tumor growth." (PMID 35686099, 2022). "The liver morphology of the FHL3 knockdown group was more similar to that of the c-MYC/AKT group, with more fatty changes around the tumor observed by H&E, which is typical of c-MYC/AKT-induced early liver lesions." (PMID 41184244, 2025). "FHL3 can interact with FHL1-2 to suppress the expression of VEGF mRNA and protein, leading to the degradation of HIF1 and inhibiting tumor angiogenesis." (PMID 35686099, 2022). "In the following experiments, the tumor growth was decreased ~50% in HGC and ~20% in SGC by the FHL3 knockdown." (PMID 34150617, 2021). "Combination treatment (FHL3 knockdown and OHP) restricted the tumor growth of about 80% in OHP-R HGC/SGC cell lines (P < 0.01)." (PMID 34150617, 2021). "However, the relationship between FHL3 and tumor EMT remains unclear." (PMID 31935687, 2020). "FHL3 is a member of LIM protein superfamily, which interacts with proteins through its LIM domains and inhibits tumor cell proliferation by Smads-mediated signaling pathway." (PMID 25659096, 2015). "By Northern analysis, FHL1, FHL2, FHL3, and FHL5 were found to be expressed at high levels in a variety of tumor cell lines, including squamous cell carcinoma, melanoma, and leukemia cell lines." (PMID 24690879, 2014). "In 50 pairs of mRNA samples and 50 pairs of protein samples from the Tongji cohort, RT-qPCR and WB results revealed that the expression of FHL3 in tumor tissues was significantly greater than that in adjacent normal tissues." (PMID 41184244, 2025). "Specifically, PIEZO1, a mechanically-gated cation channel protein, regulates the expression of extracellular matrix (ECM) remodeling genes such as TAZ and FHL3, resulting in ECM stiffening, alteration of the tumor microenvironment, and enhancement of tumor malignancy." (PMID 40535121, 2025). "Besides, FHL3 knockdown enhanced the efficacy of OHP both in HGC and SGC, which was similar to the results in subcutaneous tumor model." (PMID 34150617, 2021).
tumor (continued). "In our study, we found that decreased TGFβ/smad signaling failed to promote the tumor growth, instead of restraining tumor growth, induced by FHL3 knockdown." (PMID 31935687, 2020). "Besides, FHL3 protein has been identified as a negative regulator of HIF-1 activity, implying a mechanism by which it suppresses tumor growth." (PMID 24690879, 2014). "Furthermore, it was speculated that FHL3 can regulate the TGF-β-Smad2/3 axis and inhibit the expression of P27 to enhance tumor proliferation." (PMID 35686099, 2022).
cancer (10 papers, 2014 to 2025). A tumor composed of atypical neoplastic, often pleomorphic cells that invade other tissues. "In this review, we discuss and analyze the roles of FHL3 in cancer and hope to inspire the discovery of new diagnostic methods and optimal therapies." (PMID 35686099, 2022). "FHL3 has been previously identified as a potential susceptibility gene for CRC, with abnormal expression patterns observed in several cancers." (PMID 40321251, 2025). "Studies had shown that when PCBP2 was knocked out, the expression of FHL3 in cancer cells was increased, thus inhibiting cell growth and promoting cell apoptosis." (PMID 37814239, 2023). "In recent years, there is increasing evidence that FHL3 can also have a considerable influence on the development of cancers." (PMID 35686099, 2022). "It highlights that FHL3 plays a role in the molecular mechanisms driving the apoptosis resistance of cancer cells." (PMID 35686099, 2022). "This review focuses on the roles of FHL3 in cancer progression and discusses the interaction of FHL3 with other proteins and transcription factors." (PMID 35686099, 2022). "Cell and animal experiments also proved that down-regulation of FHL3 can decrease cancer cell metastasis." (PMID 34150617, 2021). "To verify whether the LIM4 domain of FHL3 has reproducible cancer-promoting functions, we transiently transfected LIM2, LIM3, and LIM4 deletion mutants into Hep3B cells." (PMID 41184244, 2025). "Thus, FHL3 is thought to have a dual role in cancer progression, reflecting its complex role in cancer." (PMID 38789729, 2024). "There is increasing evidence that FHL3 is abnormally expressed in different cancers." (PMID 35686099, 2022). "The expression and roles of FHL3 in different human cancers." (PMID 35686099, 2022). "Thus, FHL3 is proposed to have a dual effect on cancer progression, reflecting its complex roles in cancer." (PMID 35686099, 2022). "The previous observation that purified recombinant FHL3 protein added to cell culture media regulates cancer cell growth might be explained by the fact that FHL3 contains four 11-aa motifs." (PMID 28094252, 2017). "In summary, by establishing a link between MT-1X and FHL3, this study highlights MT-1X as a potential candidate for investigating the molecular mechanisms of cancer cell anti-apoptotic activity and also novel useful molecular targets for cancer therapy." (PMID 24690879, 2014). "Finally, the clinical significance of FHL3 for the treatment of cancers is discussed." (PMID 35686099, 2022). "In the Tongji cohort, IHC revealed that the expression of YAP in cancer tissues was greater than that in adjacent tissues, and the expression of YAP was also significantly correlated with FHL3 expression." (PMID 41184244, 2025). "Four and a half LIM domains 3 (FHL3), as a member of FHL proteins, was identified to be a novel TGF-beta-like signaling pathway and indicates a useful molecular target for cancer therapy." (PMID 37258779, 2023). "Furthermore, our previous study has demonstrated that FHL3 is required for Ang-mediated HeLa cell proliferation by inhibiting nuclear translocation of Ang, suggesting that it may also play an important role in Ang-regulated cancer cell growth and apoptosis." (PMID 24690879, 2014). "The results of the CCK-8, EdU, transwell, and scratch assays revealed that deletion of the LIM4 domain of FHL3 significantly reduced the cancer-promoting function of FHL3, whereas deletion of the LIM2 or LIM3 domain had little effect on the cancer-promoting function of FHL3." (PMID 41184244, 2025).
cardiovascular disease (2 papers, 2022 to 2024). "Based on the special structure of LIM-only proteins, FHL3 can perform significant functions in muscle proliferation and cardiovascular diseases by regulating cell growth and signal transduction." (PMID 35686099, 2022). "FHL3 (four and a half LIM protein 3) play an important role in cardiovascular disease and muscle proliferation by regulating signal transduction and cell growth." (PMID 38789729, 2024).
FHL3 also shares sentences with these, for which no sentence is quoted: lung cancer (2 papers); pancreatic ductal adenocarcinoma (2); cardiomyopathy (1); chronic granulomatous disease (1); endometrial adenocarcinomas (1); endometrial cancer (1); Hurler syndrome (1); Intellectual disability (1); microcephaly (1); microtia (1); multiple sclerosis (1); muscular dystrophy (1); osteosarcoma (1); Pectus carinatum (1); Stomach (1); Wolman disease (1).